AKAP1 (A-kinase anchoring protein 1)
Description:
Binds to type I and II regulatory subunits of protein kinase A and anchors them to the cytoplasmic face of the mitochondrial outer membrane (By similarity). Involved in mitochondrial-mediated antiviral innate immunity. Promotes translocation of NDUFS1 into mitochondria to regulate mitochondrial membrane respiratory chain NADH dehydrogenase (Complex I) activity (By similarity).
Synonyms: PRKA1; S-AKAP84; AKAP149; AKAP121; SAKAP84; AKAP84; D-AKAP1; PPP1R43; TDRD17; AKAP
Tractability: PROTAC: ubiquitination databases record sites on it; its protein half-life has been measured.
Gene: Protein-coding gene on chromosome 17 (57,085,092 to 57,121,349, forward strand). Ensembl gene ENSG00000121057.
Subcellular location: Mitochondrion outer membrane; Mitochondrion
Subcellular location (Human Protein Atlas): Mitochondria
Pathways (Reactome):
Hemostasis: Factors involved in megakaryocyte development and platelet production
Transport of small molecules: Mitochondrial calcium ion transport
Gene Ontology:
Molecular function: protein binding; protein kinase A regulatory subunit binding; RNA binding; nucleic acid binding
Biological process: antiviral innate immune response; apoptotic process
Cellular component: membrane; mitochondrion; cytosol; mitochondrial outer membrane
Genetic constraint (gnomAD): Loss-of-function variants: 33 observed, 83.95 expected, observed/expected ratio (o/e) 0.39, 90% interval 0.3 to 0.53. The upper end of that interval is the gene's LOEUF score, 0.53, which puts it in group 2 of 6, group 1 being the genes least tolerant of losing a copy. Missense variants: 961 observed, 1,196.8 expected, observed/expected ratio (o/e) 0.8, 90% interval 0.76 to 0.85. Synonymous variants: 416 observed, 492.2 expected, observed/expected ratio (o/e) 0.85, 90% interval 0.78 to 0.92.
Homologues: Orthologues: chimpanzee AKAP1 (98% identical), macaque AKAP1 (90% identical), rabbit AKAP1 (76% identical), dog AKAP1 (74% identical), pig AKAP1 (72% identical), guinea pig AKAP1 (70% identical), mouse Akap1 (68% identical), rat Akap1 (67% identical), tropical clawed frog akap1 (41% identical), zebrafish akap1b (35% identical), zebrafish akap1a (23% identical), Caenorhabditis elegans akap-1 (19% identical), and 1 more.
Diseases named in the same sentence as AKAP1 in open-access papers:
AKAP1 is named in the same sentence as 82 diseases in open-access papers, as found by Europe PMC text mining. Sharing a sentence is not in itself a finding about the gene and the disease. The quoted sentences say what the papers report.
cardiac hypertrophy (13 papers, 2014 to 2025). "As a result, the impaired AKAP1 protein is released into the cytoplasm by forming a complex with CaN, which dephosphorylates NFATc3, thereby triggering the gene expression associated with cardiac hypertrophy." (PMID 40599813, 2025). "In the present investigation, we hypothesized that loss of Akap1 exacerbates cardiac hypertrophy in response to pressure overload, leading to an accelerated progression toward HF." (PMID 29892230, 2018). "In the present study, we demonstrate for the first time that in vivo genetic deletion of Akap1 exacerbates pressure overload-induced cardiac hypertrophy development and accelerates the progression toward HF after TAC in mice." (PMID 29892230, 2018). "Collectively, these data suggest that loss of Akap1 exacerbates cardiac hypertrophy induced by pressure overload without affecting the fibrotic response." (PMID 29892230, 2018). "The fact that, only if stressed, Akap1-/- hearts exhibit pronounced cardiac hypertrophy might be in contrast with the previous notion that knockdown of AKAP121 in vitro affects per se cardiomyocyte size." (PMID 29892230, 2018). "Thus, AKAP1 may serve as a critical inhibitor of pathological cardiac hypertrophy." (PMID 40599813, 2025).
breast carcinoma (10 papers, 2014 to 2024). "Molecular, cellular, and in silico analyses of breast cancer cell lines confirmed that AKAP1 depletion is associated with impaired mitochondrial function and dynamics, concomitant with the increased glycolytic potential and invasiveness." (PMID 38399969, 2024). "Decreased AKAP1 expression is implicated in glycolytic metabolism dependent migrating cells found in invasive populations of breast cancer cells." (PMID 31991888, 2020). "Decreased AKAP1 expression was detected in the glycolytic metabolism-dependent migrating cells found in invasive populations of breast cancer cells." (PMID 38399969, 2024). "Conversely, reduction of AKAP1 expression was found to be an indicator of malignancy transition in breast cancer progression." (PMID 31991888, 2020). "AKAP1 was one of fifteen mitochondrial-related markers found to be elevated in epithelial breast cancer cells." (PMID 31991888, 2020). "Thus, reduced AKAP1 expression can be viewed as a biochemical switch toward increased breast cancer metastasis." (PMID 31991888, 2020).
heart failure (8 papers, 2014 to 2025). Inability of the heart to pump blood at an adequate rate to meet tissue metabolic requirements. "Transverse aortic constriction (TAC) generates heart failure that is exacerbated by AKAP1 gene loss, even in the heterozygous mouse." (PMID 31991888, 2020). "In AKAP1 knockout mice subjected to transverse aortic constriction (TAC), the absence of Akt activation accelerated cardiomyocyte death and worsened the progression of heart failure." (PMID 40599813, 2025). "Siah2 KO mice retain AKAP1 protein expression, compared to wildtype mice, following TAC; however, these mice are not protected against heart failure." (PMID 31991888, 2020).
myocardial infarction (8 papers, 2016 to 2022). Gross necrosis of the myocardium, as a result of interruption of the blood supply to the area, as in coronary thrombosis. "Hypoxia and myocardial infarction induced mitochondrial fission and cell death are associated with AKAP1 degradation." (PMID 31991888, 2020). "Genetic deletion of Siah2 prevents AKAP1 protein loss and protects against myocardial infarction induced cell death and loss of heart function." (PMID 31991888, 2020). "AKAP1 KO mice with permanent coronary ligation exhibit an extensive myocardial infarction size, illustrating the cardioprotective properties of this AKAP." (PMID 33923648, 2021). "Deleting AKAP1 increases mitochondrial ROS production and aggravates myocardial infarct size in mouse cardiomyocytes." (PMID 31349216, 2019). "Genetic deletion of Akap1 results in larger infarct size, worse LV systolic function, and increased mortality after myocardial infarction." (PMID 29892230, 2018). "Under conditions of myocardial ischemia, Akap1 deletion increases cardiomyocyte mitophagy and apoptosis, enhances infarct size and adverse cardiac remodeling, ultimately reducing survival after myocardial infarction." (PMID 27136357, 2016). "Furthermore, AKAP1 knock-out mice have an increased sensitivity to myocardial infarction that is demonstrated by decreases in heart function and survival." (PMID 31991888, 2020). "For example, despite no basal differences were found in mitochondrial respiration between Akap1-/- and wt hearts, following myocardial infarction, Akap1-/- mice exhibited increase levels of cardiac ROS and more prominent alterations in mitochondrial morphology compared to wt controls." (PMID 29892230, 2018). "By using a genetic model of Akap1 global deletion, we directly investigated the role of mitoAKAPs in the regulation of mitochondrial structure and function in the heart under basal conditions or after myocardial infarction." (PMID 27136357, 2016). "We have previously demonstrated that the absence of Akap1 exacerbates cardiac injury following myocardial infarction in mice, promoting mitochondrial dysfunction, enhancing ROS production and infarct size, and ultimately reducing survival." (PMID 29892230, 2018).
Obesity (6 papers, 2021 to 2024). Accumulation of substantial excess body fat. "We then further investigated the mechanism underlying the downregulation of AKAP1 in obesity." (PMID 33747723, 2021). "Using the 2,342 m5C sites derived from HeLa cells or the 3,965 mRNA sites from our union set yielded seven RBPs enriched in both comparisons, the five seen before plus FTO (Fat mass and obesity associated) and AKAP1 (A-kinase anchoring protein 1)." (PMID 38986569, 2024). "Deletion of Akap1 in mice, for example, conferred resistance to diet-induced obesity and increased energy expenditure and brown AT thermogenesis in obese mice." (PMID 38027204, 2023). "SP1 mRNA level was also significantly downregulated in adipose tissue of overweight and obese humans, which was consistent with the downregulation of AKAP1 in obesity." (PMID 33747723, 2021). "In the present study, we for the first time demonstrated that AKAP1 played a critical role in HFD‐induced obesity and systemic insulin resistance." (PMID 33747723, 2021). "To investigate the roles of AKAP1 in HFD‐induced obesity, we successfully generated AKAP1 knockout (AKAP1−/−) mice using Clustered Regularly Interspaced Short Palindromic Repeats (CRISPR) /CRISPR‐associated protein 9 (Cas9) system." (PMID 33747723, 2021). "Our results further demonstrate a critical role of BAT AKAP1 in HFD‐induced obesity and insulin resistance." (PMID 33747723, 2021). "Here, we show that AKAP1 knockout mice resist to high‐fat‐diet (HFD)‐induced obesity and insulin resistance." (PMID 33747723, 2021). "In the present study, our results revealed that AKAP1 deficiency effectively enhanced BAT activity and whole‐body energy expenditure, protecting mice against obesity and related metabolic disorders." (PMID 33747723, 2021). "Here, knockout ofAKAP1, a signaling hub on outer mitochondrial membrane, renders mice resistant to diet‐induced obesity.AKAP1 knockout significantly enhances energy expenditure and thermogenesis in brown adipose tissues (BATs) of obese mice." (PMID 33747723, 2021). "For instance, researchers observed that energy expenditure and thermogenesis were significantly enhanced in brown adipose tissue of AKAP1 knockout obese mice, which could attenuate diet-induced obesity and insulin resistance." (PMID 36274151, 2022). "Most importantly, does AKAP1 has the potential to serve as a drug target for obesity treatment?" (PMID 33747723, 2021). "Altogether, the findings demonstrate that AKAP1 functions as a brake of FAO to promote diet‐induced obesity, which may be used as a potential therapeutic target for obesity." (PMID 33747723, 2021). "Moreover, when compared with that of health controls, AKAP1 mRNA level was significantly downregulated in SAT of patients with obesity, which was effectively reversed by bariatric surgery." (PMID 33747723, 2021). "Our findings strongly suggest that AKAP1 may be used as a new target molecule for a potential therapeutic strategy of obesity." (PMID 33747723, 2021). "To further illustrate the impact of AKAP1 on obesity and insulin resistance, we restored AKAP1 expression in interscapular BAT of AKAP1−/− HFD mice by direct injection of adeno‐associated virus (AAVDJ) vector expressing AKAP1." (PMID 33747723, 2021). "Importantly, AKAP1 peptide inhibitor effectively alleviates diet‐induced obesity and insulin resistance." (PMID 33747723, 2021). "However, key questions remain: does AKAP1 function in obesity development?" (PMID 33747723, 2021). "AKAP1 elimination enhances mitochondrial ACSL1 activity and increases brown adipose thermogenesis, preventing mice from obesity." (PMID 33747723, 2021). "Collectively, our data demonstrate that AKAP1 knockout not only decreases lipid storage, but also improves circulating metabolic profile in HFD‐induced obesity, suggesting that AKAP1−/− HFD mice have greater fat utilization (i.e., fat burning)." (PMID 33747723, 2021).
Obesity (continued). "Collectively, our results indicated that AKAP1 inhibitor (2 mg kg−1 per day) strongly reduced HFD‐induced obesity and insulin resistance and had no significant adverse effects on the function of other organs." (PMID 33747723, 2021). "Importantly, restoration of AKAP1 specifically in the BAT of AKAP1−/− mice dramatically increased overall body weight and induced glucose and insulin intolerance, indicating that BAT AKAP1 expression plays a key role in HFD‐induced obesity and whole‐body metabolic dysfunction." (PMID 33747723, 2021). "Our data showed that lack of AKAP1 signaling significantly alleviated HFD‐induced adiposity, decreased ectopic fat accumulation in liver, improved blood metabolic parameters and insulin sensitivity, indicating AKAP1 as a driving force for diet‐induced obesity and metabolic dysfunctions." (PMID 33747723, 2021).
diabetes (5 papers, 2017 to 2025). "Knockdown of the AKAP1 gene protects the kidney against diabetes-induced kidney damage, which has implications for understanding the mitochondrial dysfunction observed in Bartter syndrome." (PMID 39273390, 2024). "In contrast, cardiac-specific overexpression of Akap1 restores mitochondrial function and alleviates diabetes-induced cardiac dysfunction and myocardial fibrosis by ectopically regulating NADPH-CoQ in the mitochondria and decreasing mitochondrial ROS." (PMID 37152931, 2023). "Furthermore, knockdown of the AKAP1 gene protected the kidney against diabetes-induced kidney damage." (PMID 39273390, 2024).
diabetic cardiomyopathy (4 papers, 2021 to 2025). Diabetic cardiomyopathy is a disorder of the heart muscle in people with diabetes. "Previous studies on diabetic cardiomyopathy have revealed that AKAP1 down-regulation can compromise mitochondrial respiration by impeding NDUFS1 translocation into mitochondria and promoting mitochondrial ROS generation." (PMID 39469220, 2024). "Indeed, the AKAP1 overexpression strategy has demonstrated therapeutic benefits by restoring mitochondrial homeostasis in several diseases, including diabetic kidney disease, glaucoma, and diabetic cardiomyopathy." (PMID 39469220, 2024).
glaucoma (4 papers, 2020 to 2024). Increased pressure in the eyeball due to obstruction of the outflow of aqueous humor. "Hence, modulation of AKAP1 could be considered a potential therapeutic target for neuroprotective intervention in glaucoma and other mitochondria-associated optic neuropathies." (PMID 37296658, 2023). "On the contrary, phosphorylation of Drp1 mediated by AKAP1 promotes mitochondrial fusion and rescues RGCs from glaucoma insult." (PMID 38001864, 2023). "We examined AKAP1 protein expression in the retina of a mouse model of glaucoma DBA/2J mice, which spontaneously develop elevated IOP and glaucomatous damage with age8,11,38." (PMID 32312949, 2020). "Therefore, we propose overexpression of AKAP1 and modulation of Drp1 phosphorylation at Ser637 as therapeutic strategies for neuroprotective intervention in glaucoma and other mitochondria-related optic neuropathies." (PMID 32312949, 2020). "Thus, we propose that overexpression of AKAP1 or modulation of Drp1 phosphorylation at Ser637 are potential therapeutic strategies for neuroprotective intervention in glaucoma and other mitochondria-related optic neuropathies." (PMID 32312949, 2020). "Along this line, the existence of AKAP1 in RGCs and its role in glaucoma are completely unknown." (PMID 32312949, 2020). "This review covers the current research on the role of AKAP1 in the maintenance of mitochondrial dynamics, bioenergetics, and mitophagy in RGCs and provides a scientific basis to identify and develop new therapeutic strategies that could protect RGCs and their axons in glaucoma." (PMID 37296658, 2023).
diabetic kidney disease (3 papers, 2020 to 2024). Progressive kidney disorder caused by vascular damage to the glomerular capillaries, in patients with diabetes mellitus. "The authors reported elevated mitochondrial fission in the podocytes in patients with diabetic nephropathy despite also seeing an increased expression of AKAP1." (PMID 31991888, 2020). "A recent clinical study reported that AKAP1 expression is elevated in kidney samples from patients suffering from diabetic nephropathy." (PMID 31991888, 2020).
gastric cancer (3 papers, 2020 to 2023). A primary or metastatic malignant neoplasm involving the stomach. "A-kinase anchoring protein 1 (AKAP1) is upregulated in cisplatin-resistant gastric cancer tissues and antagonizes cisplatin-induced mitochondrial fission by the phosphorylation of dynamin-related proteins 1 (DRP1), an important mitochondrial fission factor." (PMID 37445831, 2023). "Because AKAP1 restrains mitochondrial fission and reinforces cisplatin resistance in gastric cancer cells, targeting this protein by miR-148a-3 sensitizes cells to cisplatin." (PMID 37445831, 2023). "Interestingly, in a recent report about cisplatin resistance in gastric cancer, the authors discovered that the microRNA miR-148a-3p directly targets AKAP1 and leads to greater Drp1 activation, which sensitizes cancer cells to cisplatin treatment." (PMID 31991888, 2020). "Finally, through decreasing AKAP1 and RAB12 expression levels, lentiviral-mediated miR-148a-3p overexpression sensitized gastric cancer xenografts to cisplatin treatment in vivo." (PMID 36827549, 2023).
glioblastoma (3 papers, 2017 to 2022). The most malignant astrocytic tumor (WHO grade IV). "In xenograft orthotopic mouse models of glioblastoma, downregulation of AKAP1 significantly reduced cancer cell proliferation and tumor development." (PMID 28569781, 2017). "Downregulation of AKAP1 impaired mTOR pathway and inhibited glioblastoma growth." (PMID 28569781, 2017). "Expression of A-kinase anchoring protein 1(AKAP1), which attaches PKA to the cytoskeleton, as well as phosphodiesterase 1A (PDE1A), a cAMP-degrading enzyme, were shown to be increased in glioblastoma specimens, whereas the catalytic subunit of PKA was found to be decreased in high-grade gliomas." (PMID 35805104, 2022).
hepatocellular carcinoma (3 papers, 2015 to 2022). A malignant tumor that arises from hepatocytes. "One study suggested that AKAP1 can serve as a biomarker for hepatocellular carcinoma with qPCR and immunostaining evidence showing AKAP1 upregulation in tumors along with a correlation with poor prognosis." (PMID 31991888, 2020).
ischemia (3 papers, 2016 to 2020). A hypoperfusion of the BLOOD through an organ or tissue caused by a PATHOLOGIC CONSTRICTION or obstruction of its BLOOD VESSELS, or an absence of BLOOD CIRCULATION. "In the present study, we hypothesized that Akap1 deletion might affect mitochondrial structure and function in the heart, and that mitoAKAPs levels might play a crucial role in the regulation of cardiomyocyte survival under conditions of ischemia and, in turn, cardiac remodeling and survival." (PMID 27136357, 2016). "In the absence of Akap1, mitochondrial abnormalities likely increased cardiac mitophagy and, by enhancing ROS production, enhanced cardiomyocytes apoptosis during ischemia." (PMID 27136357, 2016).
myocardial ischemia (3 papers, 2016 to 2023). A disorder of cardiac function caused by insufficient blood flow to the muscle tissue of the heart. "In a mouse model of myocardial ischemia, AKAP1 deficiency promoted mitochondrial damage and mitochondrial reactive oxygen species(mtROS) production and enhanced myocardial mitochondrial phagocytosis and apoptosis." (PMID 37175819, 2023). "Similarly, a study on the critical function of AKAP1 in cardiac responses to myocardial ischemia showed that Akap1 deletion caused mitochondrial abnormalities and increased cardiac mitophagy." (PMID 37296658, 2023). "In the present study we hypothesized that Akap1 might be crucial to preserve mitochondrial function and structure, and cardiac responses to myocardial ischemia." (PMID 27136357, 2016).